AR (androgen receptor)
Diseases named in the same sentence as AR in open-access papers (continued):
Sharing a sentence is not in itself a finding about the gene and the disease.
prostate carcinoma (continued). "Blockade of AR function leads to reduced expression of several HR-associated genes such as BRCA1, RAD54L and RMI2, so that sequential treatment of a prostate cancer xenograft with the AR antagonist, enzalutamide, and the PARP-1 inhibitor, olaparib, strongly suppresses tumor growth." (PMID 33158305, 2020). "Androgen receptor (AR) signalling is essential in nearly all prostate cancers." (PMID 32047165, 2020). "FDA-approved second-generation AR antagonists for prostate cancer." (PMID 32456317, 2020). "In prostate cancer, the AR regulates the expression of genes involved in DDR." (PMID 32708219, 2020). "Polymorphic variants in the PTEN (rs2735343),PI3K (rs2699887), AKT1 (rs2494750),AR (rs17302090), and AMACR (rs3195676)genes were evaluated as possible molecular markers of susceptibility, prognosis,and progression of prostate cancer (PCa), in a case-control study." (PMID 32484847, 2020). "Recently, the emergence of an AR- prostate cancer has been reported." (PMID 32019149, 2020). "While discussion, here, centers on the use of these PET probes in breast and prostate cancers, in principle, they might also be useful in other types of cancers that are regulated by hormone action through ER, PgR, or AR." (PMID 32718075, 2020). "Androgen receptor (AR) has been reported to regulate prostate cancer stemness." (PMID 31942000, 2020). "The results demonstrated that quercetin reversed docetaxel resistance in prostate cancer via the mechanisms as follows: the activation of androgen receptor and PI3K/Akt pathway, the appearance of remarkable mesenchymal and stem-like cell phenotypes, and the P-gp expression." (PMID 32174789, 2020). "Moreover, the presence of AR in iPS87 cells provides context to and support for the need to develop curative prostate cancer treatments." (PMID 32256979, 2020). "Additionally, AR degradation has been reported to be a likely prerequisite for prostate cancer tumor shrinkage based on an in vivo experiment." (PMID 32456317, 2020). "Additionally, progression to AR independent forms of prostate cancer such as neuroendocrine prostate cancer is frequently observed post-enzalutamide treatment." (PMID 35582225, 2020). "For example, androgen receptor (AR) activates the transcription of miR-135a by directly binding to androgen response elements (AREs) in the promoter region of the MIR135A2 gene in prostate cancer cell lines; the ARE sequence, CAAGTACAGCTTGTTCTCC, is located -5,605 bp upstream of pre-miR-135a243." (PMID 32944391, 2020). "The expression of the androgen receptor (AR) and its splice variants is a crucial factor of prostate cancer biology that has not been comprehensively studied in PCa tumors." (PMID 32947898, 2020). "AR was first identified as a tumor-promoting gene in prostate cancer." (PMID 32579541, 2020). "Concerning the response to AR-directed therapies, our data suggest that primary and metastatic prostate cancers with low LumE score might be less likely to respond to the treatment and would rather benefit from alternative strategies." (PMID 31936761, 2020). "Besides possible direct interactions between AR and GR signals indicated in prostate cancer, NF-κB is known to inhibit GR activity via down-regulating the expression of target genes that are normally up-regulated by NF-κB." (PMID 32759680, 2020). "Thus, enzalutamide inhibits the AR-signaling cascade, which is essential for the survival and progression of prostate cancer cells." (PMID 32555282, 2020). "Furthermore, their upregulation in the context of CHD1 loss was reversible, as revealed by doxycycline-regulated CHD1 shRNA knockdown and was evident in three other AR-positive human prostate cancer cell lines." (PMID 32220301, 2020).
prostate carcinoma (continued). "MAGEA11 increases AR transcriptional activity during prostate cancer progression." (PMID 32626651, 2020). "To evaluate the functional impact of ERRα in prostate cancer growth, we generated both stable ERRα- overexpression and -knockdown transductants in two prostate cancer cell lines (including AR-positive: LNCaP; AR-negative: DU145) for in vitro and in vivo growth phenotype analyses." (PMID 32226548, 2020). "A previous study has reported that mutation of SUMO-conjugated sites in androgen receptor (AR) may result in an increase of AR transcriptional activity, and hence promoting cell proliferation and hypoxia-induced angiogenesis in Prostate cancer." (PMID 33240890, 2020). "The PI3K and AR signaling pathways are usually activated in prostate cancer." (PMID 32922364, 2020). "One of the current key targets of prostate cancer therapy is the androgen receptor (AR)." (PMID 32645914, 2020). "Androgen receptor (AR) has a key role in prostate cancer development and progression." (PMID 33072600, 2020). "AR has been proposed as a potential therapeutic target for BC, and the availability of AR inhibitors approved for prostate cancer treatment could constitute a therapeutic tool for specific subsets of breast cancer." (PMID 31952272, 2020). "In addition, we also found a significant overlap as well as unique ASE events induced in different prostate cancer cells treated by pharmacological inhibitor or the genomic inhibition of AR." (PMID 32820253, 2020). "Given these knowledge gaps, the goals of the current study were to determine which cells of the upper airway tract express ACE2 and TMPRSS2 and test whether their expressions could be therapeutically targeted by AR inhibitors used in prostate cancer treatment." (PMID 33310900, 2020). "For example, lncRNA LBCS was shown to suppress castration resistance and proliferation of prostate cancer cells by functioning as a scaffold of hnRNPK (Heterogeneous nuclear ribonucleoprotein K) protein and AR (Androgen receptor) mRNA to inhibit AR translation efficiency." (PMID 32351538, 2020). "Androgen receptor signaling appears to be a primary driver of prostate cancer progression, with the majority of prostate cancer deaths occurring from androgen-receptor-positive, castrate-resistant prostate cancer, making the MPC an attractive therapeutic target for this prostate cancer subtype." (PMID 32784379, 2020). "Collectively, we provide the evidence for a novel and critical mechanism of prostate cancer progression that is regulated by AR and that the treatment with AR antagonist may inadvertently promote invasion by dysregulating splicing of critical genes." (PMID 32820253, 2020). "AR is widely known to control the transcriptional landscape of prostate cancer cell." (PMID 33473254, 2020). "Here, we found that NTN3 transcription is positively regulated by both EZH2 and AR in prostate cancer (r = 0.2297 and 0.2863, respectively), suggesting that NTN3 may play a oncogenic role in prostate cancer." (PMID 32251318, 2020). "Due to the potential use of SRF as a therapeutic target in advanced prostate cancer and its relationship with AR, in this study, we tested the combination treatment of enzalutamide and CCG1423 in vitro and in LuCaP 35CR, a patient-derived xenograft (PDX) model of enzalutamide resistance." (PMID 33260953, 2020). "Androgen receptor (AR) signaling is critical at all stages of prostate cancer (PCa) progression." (PMID 31822799, 2020). "Effective suppression of recurrent prostate cancer cell proliferation by interrupting this pathway has necessitated the synthesis of multiple, specific and effective drugs with anti-hormone and/or anti-AR activity including estrogens, LHRH agonists, and more." (PMID 32256979, 2020). "Finally, DBF inhibited AR-signaling and resensitized AR-V7-positive 22Rv1 prostate cancer cells to enzalutamide, presumably due to AR-V7 down-regulation." (PMID 33271756, 2020).
prostate carcinoma (continued). "It is also suggested that targeting NFΚB might restore the sensitivity of castration-resistant prostate cancer (CRPC) cells to AR antagonist." (PMID 32235729, 2020). "Expression of AR with PTEN has also been investigated in prostate cancer." (PMID 33062889, 2020). "Moreover, overexpression or amplification of CREB5 promoted proliferation and mediated resistance to AR inhibition in metastatic castration-resistant prostate cancers." (PMID 32843066, 2020). "Cancer Genome Atlas (TCGA) analysis using 333 primary prostate carcinomas revealed that mutant SPOP-bearing tumors have the highest levels of AR-induced transcripts, indicating that upregulation of AR pathway is the most significant outcome of SPOP inactivation in PCa." (PMID 33158056, 2020). "Similarly, in prostate cancer (PCa), the activation of CAFs–androgen receptor (AR) with dihydrotestosterone modulates the secretion of pro-tumorigenic factors impacting cancer cell growth." (PMID 33553157, 2020). "Indeed, animal and in vitro data suggest that components in olive oil inhibit migration, invasion, and adhesion of prostate cancer cells, and walnuts reduce prostate tumor growth and inhibit androgen receptor expression in prostate cancer cells." (PMID 32764484, 2020). "HES6 drives castration-resistant tumour growth by enhancing the transcriptional activity of the androgen receptor, while the Prolaris signature contains many genes known to be critical for cell cycle control—both processes already known to be essential for prostate cancer growth." (PMID 32708551, 2020). "While the mechanism of AR in response to DNA damage is just beginning to be uncovered in breast cancer, the mechanistic role of AR in DNA damage repair has been more extensively characterized in prostate cancer." (PMID 33062889, 2020). "At the same time, PC-3 cells are AR-full length- and AR-V7-negative and thus might be less relevant as clinical model for prostate cancer." (PMID 32403427, 2020). "Moreover, androgens regulated PKC-δ transcription and modulated its apoptotic function in prostate cancer cells, and prenatal testosterone exposure induces hypertension in adult females via an AR-dependent PKC-δ-mediated mechanism." (PMID 32582715, 2020). "Thus DOT1L selectively regulates the tumorigenicity of AR-positive prostate cancer cells and is a promising therapeutic target for PCa." (PMID 32814769, 2020). "A key therapeutic target in prostate cancer is Androgen receptor (AR) signaling." (PMID 32645914, 2020). "Moreover, the prostate cancer-specific lncRNA prostate cancer gene expression marker 1 alters tumor metabolism by coactivating the androgen receptor and transcriptional factor c-Myc44." (PMID 32572027, 2020). "In our study, we showed that prostate cancer cells activate this lipid synthesis pathway to become more aggressive and develop resistance to commonly used therapeutic agents for advanced prostate cancer such as enzalutamide, an effective and commonly used androgen receptor (AR) targeted agent." (PMID 33187317, 2020). "Furthermore, many studies also present the effect of DHT on prostate cancer cells through non-androgen receptor pathway." (PMID 32872192, 2020). "It is reported that Cordyceps sinensis extract increased the growth of prostate cancer cells via the androgen receptor-dependent pathway, which differs from our results that CM reduced the weight of the prostate and the proliferation of prostate cancer cell lines independently of androgen levels." (PMID 33375244, 2020). "As an important caveat, we relied upon LNCaP prostate cancer cells for the SARS-CoV-2 bioassay with AR inhibitors, since we were unable to identify a lung epithelial cell line susceptible to SARS-CoV-2 infection that also had adequate AR signaling." (PMID 33310900, 2020). "Thus, MYSM1 was originally characterized as a positive regulator of androgen receptor target gene expression in human prostate cancer cell lines." (PMID 32344625, 2020).
prostate carcinoma (continued). "Treatment of LNCaP and 22Rv1 prostate cancer cells with carnosol (20–40 μM) for 48 h led to decreased expression of AR and ER-α mRNA and protein levels, as well as dose-dependently decreased cell viability with IC50 values of 19.6 μM and 22.9 μM in LNCaP and 22Rv1 cells, respectively." (PMID 33049974, 2020). "Here, the authors perform a proteomics and metabolomics characterisation of prostate cancer cells adapted to long-term resistance to AR inhibition and show rewiring of glucose and lipid metabolism, and further identify a signature associated with resistance to AR inhibition." (PMID 32427840, 2020). "Androgen receptor (AR) signaling is a major driver of prostate cancer (CaP)." (PMID 32879302, 2020). "Compounds 2a and 2b also suppressed androgen receptor expression in the prostate cancer cells." (PMID 35582221, 2020). "Moreover, in prostate cancer AR PROTACs have demonstrated more efficacy than enzalutamide in castration resistance prostate cancer, opening the door to the development of AR-PROTACs in the clinic." (PMID 32933565, 2020). "This could be attributed to the AR-mediated upregulation of glucose transporters (GLUTs) in prostate cancer cells, as demonstrated in several studies, including GLUT1, GLUT3 and GLUT12." (PMID 32927797, 2020). "Next, we will review the actions of androgens and AR in prostate cancer." (PMID 32714315, 2020). "However, the use of AR as a therapeutic tool in breast cancer treatment remains relatively limited and is mainly applied in prostate cancer." (PMID 32587770, 2020). "A recent report showed that the CRISPR-Cas9 technique of targeted androgen receptor disruption could successfully block the growth of prostate cancer cells." (PMID 32765953, 2020). "Immunocytochemistry also showed that AR expression in the nucleus of DPCs was induced by DHT but significantly reversed by PM extract, suggesting that the previous anti-androgenic results obtained from prostate cancer cell lines were exerted by regulation of AR gene expression." (PMID 32398000, 2020). "Androgen receptor (AR) signalling regulates cellular metabolism in prostate cancer." (PMID 32427840, 2020). "This manuscript will review the role of AR in various cellular processes that promote tumorigenesis and metastasis, first in prostate cancer and then in breast cancer, as well as discuss ongoing efforts to target AR for the more effective treatment and prevention of cancer, especially breast cancer." (PMID 33062889, 2020). "The androgen receptor (AR) plays a predominant role in prostate cancer (PCa) pathology." (PMID 33076388, 2020). "Furthermore, the WNT/β-catenin pathway is strongly linked to androgen/AR-directed therapy and chemotherapy resistance, thus WNT signaling presents an attractive therapeutic target for advanced prostate cancer." (PMID 32630372, 2020). "In the mentioned studies, only AR itself but neither its splice variant nor other prostate cancer related genes were evaluated." (PMID 33014830, 2020). "It is well documented that AR and steroid hormones are required for prostate cancer cell growth." (PMID 32629770, 2020). "Hence, FOXA1 contributes to AR-dependent and AR-independent processes favouring prostate cancer development." (PMID 31974375, 2020). "According to the authors, such molecular signature accounts for the “shared clinical features, resistance to AR inhibition and chemotherapy sensitivity and should serve as the foundation for a biologically-defined therapeutically relevant classification of prostate cancer”." (PMID 32344931, 2020). "AR signaling regulates cell growth, differentiation, migration and survival, and plays a critical role as a transcriptional regulator during prostate development, normal prostate tissue homeostasis, and prostate cancer." (PMID 32630372, 2020).
prostate carcinoma (continued). "In conclusion, we leveraged in vitro experiments and publicly available genomic data to support our findings that AR signaling may alter the transcriptome of prostate cancer cells by modulating global ASE." (PMID 32820253, 2020). "The Neuhaus team showed that β-ionone activated OR51E2 (not androgen receptors (AR)) causing an increase in intracellular calcium concentration in both primary prostate cancer epithelial cells and prostate cancer cell line (LNCaP)." (PMID 33321809, 2020). "Around 80–90% of prostate cancer (PCa) cases are dependent on androgens at initial diagnosis; hence, androgen ablation therapy directed toward a reduction in serum androgens and the inhibition of androgen receptor (AR) is generally the first therapy adopted." (PMID 33321757, 2020). "The AR plays a role in cell proliferation and migration in many types of cancers, including colon, breast, stomach, and bladder cancer, in addition to prostate cancer." (PMID 32847068, 2020). "The fact that single CCG1423 treatment varies in prostate cancer cell lines with different AR levels (LNCaP parental, LNCaP Abl and PC3), as well as in the same cell line (LNCaP Abl), depending on DHT stimulation, indicates that AR involvement in this process is important." (PMID 33260953, 2020). "The silence of EPHX2 could induce apoptosis in prostate cancer cells by reducing androgen receptor signalling." (PMID 33020551, 2020). "NFKB2, which is involved in aberrant activation of androgen receptor in prostate cancer cells, might be coregulated by FXR2 and HNRNPA1 proteins based on our motif enrichment analysis." (PMID 32316190, 2020). "Most metastatic prostate cancers are androgen independent with constitutively active AR signaling due to different adaptations such as AR amplification, mutations in the ligand binding domain leading to promiscuous activation, making it more difficult to treat." (PMID 32645914, 2020). "In prostate cancer, CTC enumeration remains the most extensively validated prognostic marker to date, but other clinically relevant phenotypes like androgen receptor (AR) localization or the presence of the AR-V7 splice variant are also in clinical practice." (PMID 33081135, 2020). "Indeed, we detected frequent androgen receptor alterations (46%) in prostate cancer and estrogen-receptor alterations (25%) in breast cancer." (PMID 33048619, 2020). "AR is the most studied signal in both prostate development and prostate cancer." (PMID 32678004, 2020). "AR is a protein that binds to the genome and mediates prostate cancer progression." (PMID 33322492, 2020). "Whereas the therapeutic landscape of systemic treatment for advanced prostate cancer has changed significantly with the successful introduction of AR pathway inhibitors, taxane chemotherapy remains to have a key role in the management of patients with incurable disease." (PMID 33033111, 2020). "In addition to driving AR expression, GRHL2 also acts as an AR transcriptional co-activator that enhances the oncogenic AR signaling pathway in prostate cancer progression." (PMID 32974388, 2020). "In addition, targeting the Malat1 and AR-v7 axis using Malat1-short interfering RNAs (siRNAs) in enzalutamide-resistant prostate cancer cell lines and mouse models suppressed enzalutamide-resistant prostate cancer progression." (PMID 32503170, 2020). "Therefore, the roles of AR in CAFs are still controversial and have been a hot topic in prostate cancer research." (PMID 33317606, 2020). "Furthermore, in prostate cancer all cancer epithelium was positive for ERa at the plasma membrane; and in normal prostate a small ERa+/p63+/AR− basal population suggest stem cell commitment to differentiation." (PMID 33266334, 2020). "More recently, the androgen receptor could also suppress prostate cancer cell invasion through changing the miR-4496/β-catenin signals." (PMID 33375517, 2020).